DRGX (dorsal root ganglia homeobox)
Description:
Transcription factor required for the formation of correct projections from nociceptive sensory neurons to the dorsal horn of the spinal cord and normal perception of pain.
Synonyms: PRRXL1; DRG11
Tractability: No criterion of Open Targets' tractability assessment is met for any kind of drug.
Gene: Protein-coding gene on chromosome 10 (49,364,065 to 49,398,484, reverse strand). Ensembl gene ENSG00000165606.
Subcellular location: Nucleus
Subcellular location (Human Protein Atlas): Nucleoli; Nucleoplasm; Cytosol
Gene Ontology:
Molecular function: sequence-specific double-stranded DNA binding; DNA-binding transcription factor activity, RNA polymerase II-specific; RNA polymerase II transcription regulatory region sequence-specific DNA binding; DNA binding
Biological process: neuron development; regulation of transcription by RNA polymerase II; regulation of DNA-templated transcription
Cellular component: chromatin; nucleus
Genetic constraint (gnomAD): Loss-of-function variants: 21 observed, 28.47 expected, observed/expected ratio (o/e) 0.74, 90% interval 0.52 to 1.06. The upper end of that interval is the gene's LOEUF score, 1.06, which puts it in group 4 of 6, group 1 being the genes least tolerant of losing a copy. Missense variants: 354 observed, 341.72 expected, observed/expected ratio (o/e) 1.04, 90% interval 0.95 to 1.13. Synonymous variants: 136 observed, 136.39 expected, observed/expected ratio (o/e) 1, 90% interval 0.87 to 1.15.
Homologues: Orthologues: chimpanzee DRGX (99% identical), macaque DRGX (98% identical), mouse Drgx (96% identical), rat Drgx (95% identical), pig DRGX (95% identical), dog DRGX (94% identical), guinea pig DRGX (91% identical), zebrafish drgx (75% identical), tropical clawed frog drgx (74% identical), rabbit DRGX (68% identical). Paralogues in human: PHOX2A (31% identical), PITX3 (30% identical), PHOX2B (30% identical), PITX2 (30% identical), ARX (29% identical), ALX4 (29% identical), OTP (28% identical), DMBX1 (27% identical), PITX1 (27% identical), ALX1 (26% identical), UNCX (26% identical), SHOX (25% identical), and 38 more.
Diseases named in the same sentence as DRGX in open-access papers:
DRGX is named in the same sentence as 4 diseases in open-access papers, as found by Europe PMC text mining. Sharing a sentence is not in itself a finding about the gene and the disease. The quoted sentences say what the papers report.
tumor (1 paper, 2024). "In this research, the ERGS was composed of 8 ERGs (CXCL9, CYP17A1, DRGX, ENTHD1, HAS1, LAIR2, RETN, and SPHKAP), some of which were pivotal to the tumor progression." (PMID 38600248, 2024).
DRGX also shares sentences with these, for which no sentence is quoted: anemia (1 paper); esophageal squamous cell carcinoma (1); malocclusion (1).